XIAP (X-linked inhibitor of apoptosis)
Diseases named in the same sentence as XIAP in open-access papers (continued):
Sharing a sentence is not in itself a finding about the gene and the disease.
cancer (continued). "@PMO exhibited synergistic effects in combination with oxaliplatin in a panel of αvβ3-positive cancer cells, while its toxicity is overcome by XIAP overexpression or integrin β3 silencing." (PMID 37711175, 2023). "One such treatment is the drug xevinapant, a first-in-class non-specific inhibitor of three inhibitors of apoptosis proteins (cIAP1, cIAP2, and XIAP), which sensitizes cancer cells to the cytotoxic effects of chemotherapy and radiotherapy-induced DNA damage." (PMID 37686191, 2023). "On the other hand, XIAP can drive cancer cell migration by inhibiting RhoGDP dissociation inhibitor (RhoGDI) or activating NFκB." (PMID 37391410, 2023). "A constitutive activated NF-κB signaling pathway promotes cancer cell survival in many types of cancer by leading to the activation of several anti-apoptotic genes, such as cIAP1/2, XIAP, c-FLIP, and members of the Bcl2 family." (PMID 37086261, 2023). "Akt also upregulates prosurvival proteins like X-linked inhibitor of apoptosis protein (XIAP) and Bcl-2 and downregulates proapoptotic proteins, fostering cancer progression and exacerbation." (PMID 37568796, 2023). "Excessive NF-κB signaling in cancer cells can suppress apoptosis via inducing the expression of apoptosis inhibitors such as XIAP, Mcl-1, and Survivin." (PMID 35222445, 2022). "XIAP is a member of the inhibitors of the apoptosis family of proteins (IAPs), which are overexpressed in cancer cells, and it is modulated by CK2." (PMID 36243702, 2022). "The calculations provide new insights into anticancer drug discovery since XIAP is highly expressed in cancers of diverse tumor types and is considered an attractive therapeutic target." (PMID 35956774, 2022). "XIAP is a representative sign to evade apoptotic cue-induced by chemotherapy in cancers including PC." (PMID 35652096, 2022). "X-linked IAP (XIAP/BIRC4) is one of the best characterized family members and is considered a target for therapeutic intervention in several cancers." (PMID 35721509, 2022). "As a target for cancer treatment, XIAP is abnormally expressed in cancer, thus playing a significant role in regulating patient mortality." (PMID 35959150, 2022). "It has been reported that XiaP is involved in chemoresistance, and XiaP inhibition provides a potential target for novel cancer therapies." (PMID 35475470, 2022). "Among Cu-CQ targets, it has been identified XIAP, a protein that inhibits caspases, avoiding apoptosis of cancer cells." (PMID 35309510, 2022). "It is known that lncRNA PLAC2 can regulate STAT1 activity, and STAT1 can regulate cancer cell viability by regulating the translation of XiaP and Bcl-xl." (PMID 35475470, 2022). "Embelin (2,5-dihydroxy-3-undecyl-1,4-benzoquinone) is a small-molecule inhibitor of XIAP with antioxidant and anti-inflammatory activities in several human cancer cell lines." (PMID 36430344, 2022). "It has been well documented that chemoresistance is induced by the inhibition of pro-apoptotic proteins such as PTEN, BAX and Bad and the overexpression of anti-apoptotic proteins such as p-AKT, survivin, XIAP, Bcl-2 and Bcl-xL in resistant cancer cells." (PMID 35456022, 2022). "Focusing on this effect, SMAC mimetics have been developed to neutralize cIAP1, cIAP2, and XIAP to increase the sensitivity of cancer cells to apoptosis." (PMID 36553449, 2022). "For example, a number of drug candidates targeting E3 ligases such as MDM2 and XIAP have entered clinical trials for treatment of multiple types of cancer." (PMID 35771886, 2022). "Cancer cells can evade apoptosis via upregulating the expression levels of antiapoptotic proteins such as XIAP, Mcl-1, and Survivin." (PMID 35222445, 2022). "Previous studies reported that IAPs such as cIAP1, cIAP2, and XIAP promote resistance to anoikis in several cancers, through caspase inhibition." (PMID 35256052, 2022).
cancer (continued). "Thymoquinone and TRAIL synergistically reduced the levels of XIAP (X-linked inhibitor of apoptosis), c-FLIP, BCL-2, cIAP1, and cIAP2 in HepG2 cancer cells." (PMID 35682990, 2022). "Together, these studies indicate that DDX5 acts as an upstream master regulator to control the expression of survivin, Mcl‐1, XIAP, cIAP2, c‐Myc and mKras, which are key oncogenic proteins involved in cancer development and malignant networks." (PMID 35604033, 2022). "As a result, miR-101-3p decreased XIAP and pro-caspase 3, but increased a cleaved form of caspase 3, suggesting that miR-101-3p increased the apoptosis of cancer cells." (PMID 35205710, 2022). "Previously the correlation between XIAP expression in various cancers and patient prognosis has been evaluated and a high level of XIAP has been found to correlate with a good or poor prognosis depending on cancer type." (PMID 35501389, 2022). "Another study showed that MicroRNA-489 targeting XIAP inhibits the biological progress of cancer by regulating PI3K/AKT signaling and epithelial-mesenchymal transition." (PMID 35401186, 2022). "Overexpression of XIAP compared with matched normal tissues has been reported in different cancer types, including OC." (PMID 35501389, 2022). "Taken together, the results of this study indicate that the reduction of anti-apoptotic XIAP and the induction of pro-apoptotic Bax are important mechanisms of the novel combination of C6 and DNA-damaging agents to induce apoptosis to cancer cells." (PMID 35408786, 2022). "The function of miR-122 and its associated mRNAs such as TRIM29, Bcl-W, CCNG1, CDC25A, XIAP, and ALDOA are reportedly downregulated during cancer cell progression." (PMID 36499586, 2022). "More importantly, we found that miR-137 expression level is inversely correlated with XIAP expression in five types of cancers." (PMID 35965517, 2022). "Given the growing number of studies linking XIAP to cancer, focus has shifted to the development of anti-XIAP drugs." (PMID 35992856, 2022). "XIAP and cIAP-1 are highly expressed in cancers of diverse tumor types and are considered attractive cancer therapeutic targets." (PMID 35956774, 2022). "Overexpression of BIRC4 and BIRC5 genes has been described in many cancers, and high expression of survivin and XIAP was associated with poor prognosis." (PMID 33673050, 2021). "XIAP activity in the drug-treated cells was found to be as high as that in untreated MDA-MB-231 cancer cells." (PMID 33795712, 2021). "As shown, these survival genes (BIRC5, MCL1, XIAP) were significantly increased expressions in the cancer tissues, while the apoptotic gene (CAS9) was reduced compared to the normal tissues from healthy individuals." (PMID 34307149, 2021). "The birinapant inhibits cIAP1/2 to reactivate caspase-8, and the DEBIO1143 suppresses XIAP to reactivate caspase-9 both facilitates cancer cell apoptosis, which results in synergistic anti-tumor effects in combination with cisplatin (or carboplatin)." (PMID 34026617, 2021). "For example, use of XIAP BIR domain as a target for discovering antagonists; the role of XIAP in mitochondrial membrane permeability as a target for cancer therapy; and the prognostic value of XIAP in various cancer." (PMID 34384473, 2021). "AKT then phosphorylates X-linked inhibitor of apoptosis protein (XIAP) thereby inducing evasion from apoptosis and cancer cell proliferation." (PMID 33800266, 2021). "X-linked inhibitor of apoptosis protein (XIAP), one of the components of anti-apoptotic machinery, is often overexpressed in malignant tumors and is an attractive target for cancer therapy." (PMID 33802079, 2021). "It is reported that XIAP is extremely overexpressed in several cancer cell lines of the NCI (NIH) panel." (PMID 34712428, 2021). "As supporting evidence, the overexpression of XIAP in cancer is involved in resistance to conventional chemotherapies and targeted therapies." (PMID 33809701, 2021).
cancer (continued). "Previous studies have shown that XIAP is a chemoresistance factor in mammalian cancer due to its anti-apoptotic function." (PMID 34025452, 2021). "In particular, in cancer cells, Survivin sequesters the apoptosis-inducing factor Smac/DIABLO away from binding to the X-linked inhibitor of apoptosis (XIAP), which inhibits induction of intrinsic apoptosis by blocking Caspase 9 activation." (PMID 34066833, 2021). "Studies have explored the potential role of HtrA4 in cancer cell lines, reporting that HtrA4 promotes cell death by degrading XIAP and pro-caspase 7, which was shown previously for HtrA1 and 3 in cancer cells." (PMID 34639128, 2021). "High levels of Bcl-2, XIAP and cIAPs are characteristic of many types of cancers and hence make these proteins attractive drug targets." (PMID 34943974, 2021). "Accumulating evidence from preclinical studies strongly identifies the role of XIAP in conferring therapeutic resistance in many tumors through its inhibition of apoptosis triggered by cancer therapies." (PMID 34199946, 2021). "The inhibition or decrease of XIAP in cancer cells lowers the apoptotic threshold, which in turn induces cell death and/or enhances the cytotoxic action of chemotherapeutic agents." (PMID 34199423, 2021). "Based on previous researches, miR-98-5p is available to regulate cancer development through various target genes, like XIAP, BZW1, STAT3, IGF1 and so on." (PMID 34895048, 2021). "In NPC, the NF-κB pathway is particularly active and is involved in the activation of anti-apoptotic proteins such as FLIP, c-IAP1/2 and XIAP, favoring cancer resistance and progression." (PMID 33800266, 2021). "XIAP levels are elevated in many cancer cell lines and suppression of XIAP protein expression sensitizes cancer cells to chemotherapeutic agents." (PMID 34199423, 2021). "Use of MCL-1 (myeloid cell leukemia-1) as a biomarker and target for cancer prognosis and treatment has more publications than the publications from the use of XIAP as a biomarker and target in the cancer field." (PMID 34384473, 2021). "ARTS-mimetics provide a promising novel platform for developing highly specific and potent anti-cancer drugs by targeting XIAP-and Bcl-2 for degradation." (PMID 34943974, 2021). "Survivin inhibits the activation of caspases by binding to X-linked inhibitor of apoptosis (XIAP) protein, thereby inhibiting the apoptosis of cancer cells." (PMID 34782853, 2021). "Presently, the therapeutic value of targeting XIAP in regulating the development of cancer and improving the sensitivity of chemotherapy has been testified in many types of cancer." (PMID 34712428, 2021). "Bcl-xL, survivin, and XIAP are anti-apoptotic proteins upregulated in a variety of human cancers and contributing to resistance to TNF-α35,36." (PMID 33633307, 2021). "Many pieces of research disclosed that a high level of XIAP in cancer patients expected poor diagnosis or low existence rates." (PMID 34712428, 2021). "Given that XIAP is central to apoptosis dysfunction in cancer, there is a large effort to develop anti-XIAP drugs, many of which are in clinical trials." (PMID 34199946, 2021). "XIAP overexpression in cell lines and cancer tissues has been revealed to inhibit apoptosis stimulated by a variety of apoptotic stimuli, including Fas, tumor necrosis factor, withdrawal of serum or growth factor, and radiation therapy." (PMID 34712428, 2021). "TRIM32 mediates DIAP1 levels to prevent muscle cell apoptosis during pupal development, while XIAP is similarly targeted by mammalian TRIM32 to prevent apoptosis of cancer cells." (PMID 33802079, 2021). "Different types of XIAP antagonists are generally used to repair the defective apoptosis process that can eliminate carcinoma from living bodies." (PMID 33603068, 2021). "In both models, reduction of XIAP and Bcl-2 levels in cancer cells “addicted” to high levels of these proteins initiate apoptosis." (PMID 32587235, 2020).
cancer (continued). "Curcumin also downregulates the expression of antiapoptotic proteins c-FLIP, Bcl-xL, cellular inhibitor of apoptosis protein (cIAP), and X-linked IAP (XIAP) in a ROS-dependent manner, which further induces cancer cell death." (PMID 33217990, 2020). "On the other hand, formation of the survivin-XIAP complex prevents XIAP undergoing polyubiquitination and the subsequent proteasomal degradation, thereby stabilizing XIAP in cancer cells." (PMID 32019552, 2020). "XIAP plays a role in the cancer cells’ resistance to anticancer drugs and studies on the anti-apoptotic function of XIAP in cancer cells have been focused on depleting XIAP6." (PMID 32994395, 2020). "XIAP has many other roles besides inhibiting cancer cell death, so its involvement in cancer cell biology should be explored further." (PMID 32994395, 2020). "As SM induce the rapid degradation of BIRC2 and XIAP in cancer cells and HIV-TCM19,24,25,29–31, we evaluated the ability of the SM LCL-161, AT-406, and birinapant to induce BIRC2 and XIAP degradation in uninfected macrophages and HIV-Mφ." (PMID 32719312, 2020). "It was reported that survivin and XIAP can form a heterocomplex to stabilize both of them and synergistically antagonize the activity of Caspase 9 to inhibit apoptosis in cancer cells." (PMID 32381104, 2020). "Of note, the increased XIAP mobility was detected in both primary cancers and in hepatic metastases, indicating that the level of biologically functional copper was higher in the malignant cells." (PMID 32060280, 2020). "Apart from its function as a caspase inhibitor, XIAP in cancer cells inhibits cell adhesion, migration, and motility by controlling Rho GTPase proteins, such as Rac1 and Cdc428–13." (PMID 32994395, 2020). "Circ_0000282 indirectly up-regulated XIAP expression by adsorbing miR-192, thereby playing a role in promoting cancer in OSA." (PMID 33097010, 2020). "As a vital decider on cell survival, XIAP is involved in the regulation of cancer initiation, promotion and progression." (PMID 33138314, 2020). "In recent years, intense efforts were made to target IAPs and in particular XIAP for cancer therapy." (PMID 32182843, 2020). "In either model, reduction of both XIAP and Bcl-2 in cancer cells “addicted” to high levels of these proteins stimulates apoptosis." (PMID 32587235, 2020). "Given the detrimental nature of XIAP and mounting data linking XIAP to various types of cancers, focus has been directed to the development of anti-XIAP drugs." (PMID 33138314, 2020). "XIAP contributes to the tumor development and increases the resistance of oncogenic cells to cancer treatments, among which the most extensively studied are chemotherapy and radiotherapy." (PMID 33138314, 2020). "Significantly, over-expression of both XIAP and Bcl-2 contributes to tumorigenesis and have become major targets for developing anti-cancer therapeutics." (PMID 32587235, 2020). "These discoveries about XIAP’s unconventional roles in cancer were supported by this study which identified another molecular mechanism for the XIAP-mediated inhibition of cancer cell proliferation and invasion through the degradation of OGT." (PMID 32994395, 2020). "In particular, BIRC6 and XIAP were positively correlated with REST expression across all cancer types except XIAP in PCPG." (PMID 31964418, 2020). "Smac mimetics were originally optimized to target XIAP in cancer therapies, though more recently, Smac mimetics have been developed to target both XIAP and cIAP1, as well as other IAPs." (PMID 33205060, 2020). "The IAP family (e.g., cIAP-1, Survivin and XIAP) and the Bcl-2 protein are anti-apoptotic proteins that, in response to a variety of pro-apoptotic stimuli, aim to prevent apoptosis in cancer cells, where they can be overexpressed." (PMID 32290047, 2020). "Since many types of cancers become “addicted” to high levels of Bcl-2 and/or XIAP, we propose that drugs that can promote their degradation would be of significant interest." (PMID 32587235, 2020).
cancer (continued). "Generally, XIAP exhibits high expression, specifically in cancer cells, contributing to cancer progression by modifying cell’s resistance to death." (PMID 33138314, 2020). "It was also demonstrated that circ_0000282 facilitated OSA cell proliferation and impeded cancer cell apoptosis by regulating miR-192/XIAP axis." (PMID 33097010, 2020). "Downregulation of XIAP increases the apoptosis of cancer cells induced by multi-factor stimulation, including tumor necrosis factor-related apoptosis-inducing ligand (TRAIL) and anti-tumor drugs." (PMID 32062612, 2020). "The characterization of XIAP to be a drug target for cancer therapy occurred more than ten years ago." (PMID 33138314, 2020). "Yes-associated protein (YAP) and c-MYC were selected to further confirm the specific contribution of O-GlcNAc-modified XIAP-dependent OGT degradation in cancer cells because both proteins are potent oncogenic factors and regulated by O-GlcNAc modification." (PMID 32994395, 2020). "Apart from how XIAP contributes to cancer development, the mechanisms behind XIAP stabilization and up-regulation needs to be understood." (PMID 33138314, 2020). "Next, the effect of overexpressed XIAP on cancer cell invasion was examined because XIAP-induced OGT degradation decreased Snail1 levels which in turn upregulated E-cadherin expression." (PMID 32994395, 2020). "In this review, the basic functions of XIAP, its regulatory role in cancer, anti-XIAP drugs and recent findings about RNA–XIAP interactions are discussed." (PMID 33138314, 2020). "Smac-mimetics can target tumors with high levels of cIAPs, whereas ARTS-mimetics are expected to be effective for cancers with high levels of XIAP." (PMID 32182843, 2020). "In contrast, the RING domain of XIAP exhibits E3 ubiquitin ligase activity and this activity is required for the XIAP-mediated cancer cell migration." (PMID 32019552, 2020). "In particular, drugs targeting RIPK1, TRAIL and XIAP had opposite correlations in different cancer types with the same IAP." (PMID 31964418, 2020). "Here, we made a comprehensive search using the public database miRcode and Starbase, and miR‐22‐3p was identified to be a target gene of MALAT1, as well as an upstream gene of XIAP in cancer." (PMID 33135336, 2020). "PI3K/AKT/mTOR inhibition via various molecules or compounds have been shown to induce cancer cell apoptosis through reduction of mitochondrial membrane potential, inactivation of XIAP, activation of caspase-3, upregulation of BAX and downregulation of Bcl-2." (PMID 32443471, 2020). "We previously showed that small peptides encompassing the binding site of ARTS to XIAP can promote cell death in cancer cells." (PMID 32182843, 2020). "From the chart downloaded from UALCAN, we can also observe the overexpression of XIAP, cIAP1, and cIAP2 at the mRNA level in some types of cancer." (PMID 32325691, 2020). "Several previous studies have been demonstrated that XIAP is a potential therapeutic target for various types of cancer, as an overexpression of XIAP is found in many cancer cells." (PMID 32106546, 2020). "RNA–XIAP interaction is a focus, which has enriched the general profile of XIAP regulation in human cancer." (PMID 33138314, 2020). "Our previous studies have shown that CDKI‐73 induced apoptosis by targeting short‐lived pro‐survival mRNA, such as Mcl‐1, XIAP and Bcl‐2 in cancer cells." (PMID 31398271, 2019). "At the normal expression level of XIAP, 1*105 molecules per cell, the cancer cell is reliant on MOMP for apoptosis." (PMID 31685811, 2019). "Our study provides the rationale of targeting XIAP with sunitinib to enhance TRAIL-mediated apoptosis in cancer cells where XIAP plays a pivotal role in driving apoptotic resistance." (PMID 31248045, 2019). "High level expression of XIAP has been detected in various kind of cancers and has been shown to relate to chemoresistance, progression of disease and poor prognosis." (PMID 31548877, 2019).